SLC22A4 (solute carrier family 22 member 4)
Diseases named in the same sentence as SLC22A4 in open-access papers (continued):
Sharing a sentence is not in itself a finding about the gene and the disease.
autoimmune disease (2 papers, 2006 to 2015). A disorder resulting from loss of function or tissue destruction of an organ or multiple organs, arising from humoral or cellular immune responses of the individual to their own tissue constituents. "Despite all these evidences of involvement of SLC22A4 in human autoimmune disease, the association of SLC22A4 with AITD has never been studied." (PMID 26329403, 2015). "Although previous studies suggested rs3792876’s involvement into immune disorders, due to pathophysiological difference between AITD and other autoimmune diseases, it’s highly possible that SLC22A4 may be genetically totally unrelated to GD, HT, or AITD." (PMID 26329403, 2015).
cystinuria (2 papers, 2021 to 2025). Cystinuria is a renal tubular amino acid transport disorder characterized by recurrent formation of kidneys cystine stones. "Evaluating L-Erg in combination with current standard therapies, as well as investigating genetic factors such as SLC22A4 variants that may affect drug response, will be important to personalized treatment and define its role in the clinical management of cystinuria." (PMID 41142409, 2025). "As L-Erg is transported by OCTN1 (Slc22a4) and as Slc22a4−/− mice lack L-Erg in the kidneys, we crossed the Slc22a4−/− mice with our cystinuria mice model (Slc7a9−/−) looking for differences in the rate of lithiasic mice related to OCTN1 loss." (PMID 34573056, 2021).
Hypertension (2 papers, 2014 to 2025). The presence of chronic increased pressure in the systemic arterial system. "SLC22A4 was also causally associated with hypertension (OR = 1.01; 95% CI, 1.005–1.014; P = 3.46 × 10−5) and with SAH (Pfdr = 1.38 × 10−4)." (PMID 38977622, 2025). "TNFSF12 promoted IA and SAH, SLC22A4 increased the risk of IA rupture leading to SAH, and SPARC was a risk factor for ICH, for which hypertension may be a potential mediator." (PMID 38977622, 2025). "Whereas hypertension, as an independent risk factor for SAH, may mediate the ability of SLC22A4 to cause SAH, a significant association between SLC22A4 and hypertension was also demonstrated in our study." (PMID 38977622, 2025). "Our study provides strong evidence that TNFSF12, SLC22A4, and SPARC may be potential risk factors for hemorrhagic stroke and that their induction of hypertension may be involved in potential pathogenesis." (PMID 38977622, 2025).
intracranial aneurysm (2 papers, 2024 to 2025). "The inhibition of TNFSF12, SLC22A4, and SPARC can reduce the risk of intracranial aneurysm, subarachnoid hemorrhage, and intracerebral hemorrhage." (PMID 38977622, 2025).
neuroblastoma (2 papers, 2014 to 2022). Neuroblastoma (NB) is the most common solid, extracranial childhood tumor. "The screening results of the RF classifier showed that EPS8L1, PLCD4, CHD5, NTRK1, and SLC22A4 were the most characteristic DEG genes among high-risk neuroblastoma-related genes." (PMID 35911385, 2022). "The screening results of RF showed that EPS8L1, PLCD4, CHD5, NTRK1, and SLC22A4 were the feature differentially expressed genes (DEGs) of high-risk neuroblastoma." (PMID 35911385, 2022).
type 1 diabetes (2 papers, 2006 to 2023). "The purpose of this study was to investigate the influence of the SLC22A4 and SLC22A5 genes in type 1 diabetes risk in the Spanish population." (PMID 16796743, 2006). "We tested six polymorphisms in the SLC22A4 and SLC22A5 genes and in five of them no significant independent association with type 1 diabetes could be found." (PMID 16796743, 2006).
Atopic Dermatitis (1 paper, 2014). "Our conditional analyses suggest an independent effect at the SLC22A4 gene for Atopic Dermatitis." (PMID 25477900, 2014).
colonic disease (1 paper, 2010). "Colonic disease was significantly associated with disease SNP rs7517847 (IL23R) (p<0.05) and colonic and ileal/colonic disease was significantly associated with disease SNP rs125221868 (IBD5) and SLC22A4 & SLC22A4/5 variants (p<0.05)." (PMID 21079743, 2010).
coronary artery disease (1 paper, 2022). "In addition, SNPs in OCTN1 (SLC22A4), a cation/carnitine transporter postulated to be localized inside mitochondria have been also linked to coronary artery disease." (PMID 36613915, 2022).
hemorrhagic stroke (1 paper, 2025). A stroke caused by a bleed on the brain. "Our study revealed that six druggable genes were associated with hemorrhagic stroke, and the inhibition of TNFSF12, SLC22A4, and SPARC had preventive effects against hemorrhagic strokes." (PMID 38977622, 2025). "We can conclude that TNFSF12, SLC22A4, and SPARC may induce IA, SAH, and ICH and that blocking these targets may have a protective effect against hemorrhagic stroke." (PMID 38977622, 2025). "Our study provides the first comprehensive exploration of targets involved in SAH and ICH using eQTL data to provide genetic support for hemorrhagic stroke drug development and is the first to report that TNFSF12, SLC22A4, and SPARC have preventive effects on IA, SAH, and ICH." (PMID 38977622, 2025).
Obesity (1 paper, 2021). Accumulation of substantial excess body fat. "All these maneuvers did not change the association between SLC22A4 SNPs, obesity, and tooth loss." (PMID 32964310, 2021).
ovarian carcinoma (1 paper, 2016). A malignant neoplasm originating from the surface ovarian epithelium. "The HCMECs express relatively low levels of the high-affinity OCTN1/SLC22A4 and OCTN2/SLC22A5 transporters and relatively high levels of the high-affinity OCT1/SLC22A1 and low-affinity OCT2/SLC22A2 transporters compared to the HBMECs and A2780 ovarian carcinoma cells." (PMID 27543060, 2016).
psoriasis (1 paper, 2015). An autoimmune condition characterized by red, well-delineated plaques with silvery scales that are usually on the extensor surfaces and scalp. "rs10782001 in FBXL19, rs1975974 in C17orf51, rs12720356 in TYK2, rs3792876 in SLC22A4, rs6908425 in CDKAL1, and rs13437088 in HLA-B/MICA have previously been associated with psoriasis, but not with type I psoriasis." (PMID 26613086, 2015).
schizophrenia (1 paper, 2022). A major psychotic disorder characterized by abnormalities in the perception or expression of reality. "Alterations in solute carrier family genes, such as SLC2A6, SLC1A5, and SLC22A4, have been implicated in the impairment of the synaptic transmission, which seems relevant to the pathology of schizophrenia." (PMID 35012632, 2022).
Stroke (1 paper, 2023). Sudden impairment of blood flow to a part of the brain due to occlusion or rupture of an artery to the brain. "Furthermore, the association of ID3 and SLC22A4 with immune cells may be a new direction for post-stroke immunotherapy." (PMID 38112574, 2023). "Analysis of the discovery dataset (GSE58294, GSE22255) showed a significant decrease in ID3 expression and a significant upregulation of SLC22A4 expression in stroke patient samples compared with controls." (PMID 38112574, 2023).
cancer (13 papers, 2017 to 2024). A tumor composed of atypical neoplastic, often pleomorphic cells that invade other tissues. "SLC22A4, a solute carrier protein, has been associated with drug disposition and response in cancer therapy, reflecting its role in modulating chemotherapeutic efficacy and resistance mechanisms in tumors." (PMID 38962012, 2024). "There are reports about oncogenetic variants in the SLC22A4 (OCTN1) and SLC22A5 (OCTN2) genes to be linked to prolonged time to progression or optimal response to imatinib treatment in different cancers." (PMID 32806706, 2020).
tumor (4 papers, 2013 to 2020). "SLC22A4, which is an organic cation transporter and has been previously identified to confer cellular uptake and sensitivity to anti-tumor drugs, may play a role in the pharmacokinetics of CDDP and GEM." (PMID 23451142, 2013). "On the other hand, SLC6A6 and SLC22A4 are transporters, SART3 is a tumor rejection antigen, VPS41 is involved in organelle development, SEMA4C is involved in axon guidance, and SHMT1 is an enzyme with involvement in glycine, serine, and threonine metabolism." (PMID 30973896, 2019). "Another five genes that were up-regulated with tumor progression showed further increased expressions after chemotherapy (CRISP3, KCNMA1, BDNF, SLC22A4, SYN2)." (PMID 23451142, 2013).
inflammation (2 papers, 2020 to 2022). Aberrant reaction of the microcirculation characterized by movement of fluid and leukocytes from the blood into extravascular tissues. "Oct1-3 (Slc22a1-3), Octn1 (Slc22a4), Oat1, Oat3 and Rst (Slc22a12) knockout (KO) mice are fertile, viable and show no general phenotypic abnormalities except for the Oat3 KO’s decreased blood pressure, serum metabolite changes, and the Octn1 KO’s increased susceptibility to intestinal inflammation." (PMID 32183456, 2020). "Moreover, the gene SLC22A4, which encodes OCTN1, is located near the genes regulating inflammation, and it was found that the expression of OCTN1 mRNA in the immune cells was increased in some patients with chronic inflammation." (PMID 35370675, 2022).
cerebral artery (1 paper, 2023). "RT-qPCR, western blot, and immunofluorescence revealed a significant decrease in ID3 and a significant increase in SLC22A4 in the middle cerebral artery occlusion group." (PMID 38112574, 2023).
neurodegenerative disease (1 paper, 2024). A disorder of the central nervous system characterized by gradual and progressive loss of neural tissue and neurologic function. "Apparently, LRRN3 may be involved in the development of neurodegenerative processes in PD, while the MEF2C and SLC22A4 genes might be involved in the development of general compensatory processes typical for various neurodegenerative diseases." (PMID 39061965, 2024).
neurological disorders (1 paper, 2024). "Increased SLC22A4 expression in both PD patients and neurological controls may be a protective mechanism that alleviates the symptoms of neurological disorders." (PMID 39061965, 2024).
SLC22A4 also shares sentences with these, for which no sentence is quoted: colitis (8 papers); ulcerative colitis (6); acute myeloid leukemia (4); carnitine deficiency (3); liver fibrosis (3); Parkinson disease (3); autoimmune thyroid disease (2); colorectal cancer (2); inflammatory bowel disease 5 (2); kidney disease (2); steatosis (2); abscess (1); alcohol liver disease (1); arterial embolism (1); atrial fibrillation (1); autosomal recessive deafness (1); breast carcinoma (1); cardiovascular disease (1); chronic kidney disease (1); chronic obstructive pulmonary disease (1); deep vein thrombosis (1); diabetic kidney disease (1); embryonic carcinoma (1); esophageal squamous cell carcinoma (1); gastroduodenal ulcer (1); gastrointestinal disorders (1); heart failure (1); hyperuricemia (1); hypothyroidism (1); immune disorders (1).
A further 18 diseases each share a sentence with SLC22A4 in 1 paper.